CSPG4 (chondroitin sulfate proteoglycan 4)
Diseases named in the same sentence as CSPG4 in open-access papers (continued):
Sharing a sentence is not in itself a finding about the gene and the disease.
tumor (continued). "Thanks to these features and to its poor expression in adult healthy tissues, CSPG4 represents an ideal oncoantigen and thus an attractive target for anti-tumor immunotherapy." (PMID 28668095, 2017). "A separate study of a CAR targeting chondroitin sulfate proteoglycan 4 (CSPG4) showed reduced tumor growth in a xenograft model of the HNSCC cell line PCI-3024." (PMID 27239282, 2016). "CSPG4 positive tumor cells, incubated together with PBMC and r28M, underwent a caspase 3 and 7 related pathway, strong signals of the caspase 3 subunits (17 and 19 kDa) and caspase 7 subunit (20 kDa) were detected (lane 3)." (PMID 26469402, 2015). "The chondroitin sulfate proteoglycan 4 (CSPG4) is a cell-surface proteoglycan involved in the activation of several signaling pathways playing an important role in tumor cell proliferation, survival, and migration as well as in tumor progression." (PMID 25997619, 2015). "Since it is highly expressed on tumor cells and has restricted distribution in normal tissues, CSPG4 has been used as a target of antibody-based immunotherapy." (PMID 25997619, 2015). "The killing of CSPG4 positive tumor cells was enhanced by 11% and 17% (0.0067% and 0.0013% Tween® 80) and 28% (0.0013% Na-deoxycholate), respectively, without interfering with cell growth." (PMID 26469402, 2015). "Cell viability measurements revealed that the r28M dimer generally exhibited the highest efficiency in inducing PBMC to kill CSPG4 positive tumor cells." (PMID 26469402, 2015). "After 48 hours 43% of CSPG4 positive tumor cells were still alive, whereas only 25% viable tumor cells were left after incubation for 72 hours." (PMID 26469402, 2015). "These effector cytokine production was specific to tumor lines expressing CSPG4, as minimal cytokine was release in coculture with H1299 cells or with GFP vector transduced cells." (PMID 25197555, 2014). "Monoclonal antibodies recognising melanoma-associated antigens such as CSPG4/MCSP and targeting elements of tumour-associated vasculature (VEGF) have constituted long-standing translational approaches aimed at reducing melanoma growth and metastasis." (PMID 24969320, 2014). "This illustrates that mAb9.2.27 bound to the NG2/CSPG4 positive tumour cells was required to trigger ADCC mediated cytotoxicity and facilitate the efficacy of NK cells in this GBM model." (PMID 25268630, 2014). "Another early approach aimed at overcoming immunological unresponsiveness to CSPG4 entailed designing anti-idiotypic antibodies to act as immunogens by mimicking tumour antigen epitopes known to be recognised by patient humoral responses." (PMID 24969320, 2014). "Surficial retention of CSPG4 on expanding tumor cells improves its standing as a potential therapeutic target." (PMID 24932730, 2014). "Herein we expand upon that work by utilizing different murine mAbs reactive against CSPG4 to construct CARs that target cell lines from multiple tumor histologies as well as cancer stem cells (CSC)." (PMID 25197555, 2014). "Monoclonal antibodies and antibody fragments have been examined with the view to develop targeted therapies against CSPG4-expressing tumours." (PMID 24969320, 2014). "Differences were particularly accentuated when considering the apparently diverse glycosylation patterns of the recognized NG2/CSPG4 isoforms of pericytes/OPCs versus tumour cells, i.e. as in the case of mAbs 2166G4 and 2172D6 versus mAb 2161F9." (PMID 24386429, 2013). "We have previously shown that NG2/CSPG4 was located on the tumor cells as well as their angiogenic vasculature on pericytes." (PMID 24127551, 2013). "CSPG4 was elevated 3.2-fold (P < 0.02) in tumor tissue over normal tissue among 14 subjects, while CHST11 was elevated 1.8-fold (P = 0.034) in tumor over normal among 15 subjects." (PMID 21658254, 2011). "Several membrane PGs, including SDC-1, SDC-4, NRP-1, and CSPG4 can potentially present GAG chains on the surface of tumor cells." (PMID 21658254, 2011).
tumor (continued). "The CSPG4 gene encoding the NG2 proteoglycan, is turned off upon terminal differentiation, but is aberrantly re-expressed by several tumour types." (PMID 21829586, 2011). "Furthermore, CSPG4 targeting through a chimeric human/dog (HuDo)-CSPG4 DNA vaccine has shown promising anti-tumor activity in highly translational comparative OSA models, including human xenograft mouse models and canine patients with spontaneous OSA." (PMID 41375047, 2025). "Importantly, both CSPG4 and B7-H3 have a low distribution on normal tissues, thus limiting ‘on-target off-tumor’ CAR T-related toxicities." (PMID 40847369, 2025). "Early investigations demonstrated the anti-tumor effects of anti-CSPG4 mAbs in vitro and in vivo." (PMID 41375047, 2025). "However, self-TAAs overexpressed on tumor cells, such as CSPG4, are generally well tolerated by the host immune system." (PMID 41375047, 2025). "The HA-based hydrogel containing CAR-T cells was also used for implantation into the tumor cavity: those HA hydrogel implants gradually released CAR-T cells targeting chondroitin sulfate proteoglycan 4 and this approach enabled to prevent the post-surgery tumor recurrence in a murine model." (PMID 39996879, 2025). "CSPG4 plays a role in maintaining the integrity of blood vessels and may regulate tumor angiogenesis by interacting with VEGFA pathways." (PMID 40710334, 2025). "The importance of evaluating the antibody Fc region with regard to anti-tumour efficacy was highlighted in several studies which evaluated anti-CSPG4 antibodies with human Fc domains, which allowed the study of antibody effector functions in relation to efficacy." (PMID 39409881, 2024). "Moreover, some studies have reported that CSPG4 is expressed in the endothelial cells and affects vascular formation in the tumor microenvironment." (PMID 38338902, 2024). "Furthermore, CSPG4’s expression level in tumor tissue sections was significantly higher than that in non-tumor control tissue sections." (PMID 37432459, 2023). "Furthermore, CSPG4 has been shown to play a pivotal role in promoting tumor proliferation and metastasis." (PMID 38015710, 2023). "CSPG4 was investigated as a potential immunotherapy target due to its restricted expression in normal tissues, increased expression in tumors at different disease stages, and ability to support tumor growth and progression." (PMID 36768830, 2023). "This is evident by the release of cytokines and the upregulation of co-stimulatory cell-surface markers upon monocyte activation by CSPG4 IgE in vitro, and tumor infiltration of macrophages and immune signaling pathway activation in tumors of CSPG4 IgE-treated mice." (PMID 37185332, 2023). "This is consistent with CSPG4′s role in the motility and migration of tumor cells." (PMID 36768830, 2023). "However, the potential for off-tumor/on-target activity, such as against pericytes, is considered a serious caveat for clinical testing of aggressive anti-CSPG4-dependent approaches." (PMID 36768830, 2023). "Convincingly disproving the notion that CSPG4 expression on normal tissues might pose a problem when targeting this molecule as a tumor antigen, is the inability of CSPG4-specific CAR T cells to identify and lyse normal cells in vitro." (PMID 36721153, 2023). "Similarly, tumor growth was significantly restricted in mice treated with CSPG4 IgE, versus the PBS and isotype control IgE groups (right)." (PMID 37185332, 2023). "Therefore, concerns related to the tumor specificity and on-target/off-tumor activity of therapeutic approaches hamper the development of clinical strategies using anti-CSPG4 mAbs." (PMID 36768830, 2023). "CSPG4 may induce on-target/off-tumor toxicity in TNBC immunotherapy and promote CSPG4-CAR in the pericytes around tumor-associated endothelial cells." (PMID 37457288, 2023).
tumor (continued). "Previous work suggested that glycans contribute to the binding of specific anti-CSPG4 antibodies to tumor cells, but the specificity and importance of this contribution are unknown." (PMID 36768830, 2023). "Therefore, the potential for off-tumor activity remains a serious concern when targeting CSPG4 therapeutically." (PMID 36768830, 2023). "Since the Fab-mediated and Fc-mediated effector functions of anti-tumor IgE antibodies directed against tumor cells may restrict cancer cell growth, we investigated whether CSPG4 IgE could impair cancer cell function in vitro." (PMID 37185332, 2023). "Furthermore, antigen-dependent antibody-promoted interactions between monocytes and tumor cells were important for the induction of pro-inflammatory signals and CSPG4 IgE ADCC was impaired by a PTK2 inhibitor." (PMID 37185332, 2023). "Furthermore, human tumor growth restriction by CSPG4 IgE in human PBMC engrafted mice was ablated by depletion of monocytes from PBMCs prior to injection." (PMID 37185332, 2023). "As hypothesized, CSPG4-expressing tumor cells were only efficiently lysed when both CCR and CAR engaged their target antigens simultaneously." (PMID 37901209, 2023). "In contrast, CSPG4 CAR T or DSF/Cu+IR + CD19 CAR T treatment inhibited tumor growth, but neither treatment caused complete tumor regression." (PMID 37714830, 2023). "We characterized CSPG4 IgE for its anti-tumor functional attributes." (PMID 37185332, 2023). "Finally, our in vitro and in vivo findings confirm that co-expression of a CD20-directed CCR successfully potentiated the anti-tumor cytotoxicity of CSPG4-CAR T cells in a CCR- and CAR- target antigen-dependent manner." (PMID 37901209, 2023). "Further studies may focus on the 2C/165 TCR due to its higher avidity that translated also into increased reactivity against HLA-C*07:01+/CSPG4+ tumor cell lines." (PMID 37849763, 2023). "Building on our proof-of-concept data, targeting decitabine-mediated CSPG4 upregulation via CAR-T cells could be assayed in a variety of different tumor entities." (PMID 36291817, 2022). "The series of tested cell lines included several GIST cell lines derived from patients in relapse after conventional treatment: all cell lines showed CSPG4 expression at the cell surface, and tumor elimination was strictly dependent on the expression level on tumor cells." (PMID 35267618, 2022). "In addition to working with membrane-bound factors to transmit signals from the ECM, CSPG4 has been shown to mediate cell function and subsequent pathology during tumour development via direct binding of ECM components." (PMID 36428658, 2022). "In Stage I and II tumours, high CSPG4 expression may reflect an initial inflammatory response, and recruitment of bone marrow-derived cells, as well as tumour neovasculature, to the developing tumour." (PMID 36428658, 2022). "Taken together this puts CSPG4 squarely within the p-EMT subtype, which is unsurprising as these p-EMT cells are localised to the leading edge of a tumour and are associated with increased invasiveness and motility, both of which are closely linked to CSPG4 function." (PMID 36428658, 2022). "Importantly, accumulating evidence implicates a role of CSPG4 in tumor evolution by providing growth signals and by counteracting apoptotic stimuli." (PMID 36291817, 2022). "Notably, TNC binds soluble fibronectin and blocking TNC binding to CSPG4 via Syndecan-4 addition has been shown to reduce tumour cell adhesion and migration." (PMID 36428658, 2022). "However CSPG4 is an attractive target in cancer cells due to its well-defined role in tumor cell growth, invasion and metastasis, and its restricted expression in healthy tissue." (PMID 36110930, 2022). "However, in our reanalysis of recently published transcriptome data, we have demonstrated that the tumour microenvironment is a key consideration in these studies, with the degree of difference in CSPG4 expression reduced when cells are examined in culture." (PMID 36428658, 2022).
tumor (continued). "In this instance, tumour mRNA for CSPG4 inversely correlated with metastatic tumour spread." (PMID 36428658, 2022). "“CSPG4-high” GISTs displayed higher scores for immune and stromal signatures (respectively, p = 4.20 × 10−2 and p = 4.83 × 10−2), while “CSPG4-low” tumors showed higher tumor purity (p = 3.65 × 10−3)." (PMID 35267618, 2022). "As examples, chondroitin sulfate proteoglycan 4 (Cspg4) regulates tumor growth and metastasis." (PMID 35565312, 2022). "But our present data suggest that a treatment based on CSPG4-CAR.CIKs infiltrating cells that will target "CSPG4-high" tumor cells could be interesting if some aspects responsible for the immune desert can be overcome first." (PMID 36221119, 2022). "The expressions of VEGFA and CSPG4 genes and also human β-actin as the reference gene were examined using the quantitative real-time polymerase chain reaction method in the formalin-fixed paraffin-embedded tumor tissues." (PMID 36422502, 2022). "The prognostic value of CSPG4 expression is likely tumor type-dependent." (PMID 36221119, 2022). "The drop in CSPG4 expression in late tumours which have metastasised (undergone an angiogenic switch) may reflect this change in tumour architecture, as well as an overall reduction in widespread tissue remodelling." (PMID 36428658, 2022). "Importantly, CSPG4 specific monoclonal antibodies and adoptive cell transfer therapies targeting CSPG4 have been effective in pre-clinical models by inhibition tumor growth and proliferation, making it a promising target for clinical application." (PMID 36110930, 2022). "CSPG4 has been studied as a target antigen in cancer immunotherapy based on its limited expression level in normal tissues and overexpression and supporting roles in cancer progression and invasion in various types of neoplasms, including TNBC." (PMID 36483567, 2022). "In addition, a first evidence showed in vitro the anti-tumor efficacy of CIK cells expressing a CAR specific for CSPG4 antigen in high grade STS." (PMID 33806296, 2021). "In aggregate, CSPG4-CAR-T cells have the potential to mount a concerted attack against various targets, including primary TNBC cells, stromal cells, and cancer-associated fibroblasts, which assume a crucial role in maintaining the tumor microenvironment." (PMID 33442419, 2021). "CSPG4 is a cell surface type I transmembrane protein critical for tumor progression and metastasis." (PMID 32894202, 2020). "A375 tumor cells harvested from the isotype-(PDD)-treated mouse and from the anti-CSPG4-(PDD)-treated mice were equally susceptible to ex vivo treatment with anti-CSPG4-(PDD)." (PMID 32331483, 2020). "Furthermore, CSPG4-mediated activation of one of the same integrins induced chemoresistance and survival in tumor cells." (PMID 32984308, 2020). "The high expression of B7-H3 and chondroitin sulfate proteoglycan 4 (CSPG4) across multiple tumor types such as prostate, breast, placenta, liver, colon, and lymphoid organs and restricted expression in normal tissues makes them attractive targets for immunotherapy." (PMID 32894202, 2020). "Furthermore, a single injection of 5 mg/kg of anti-CSPG4-(PDD) led to complete tumor regression of A375 xenografts in 4/7 mice for 70 days following treatment in the absence of overt toxicities." (PMID 32331483, 2020). "In order to obviate concerns about potential on-target/off-tumor toxicities, we have previously demonstrated that transient transfection of T cells with CSPG4-CARs using mRNA electroporation might be an effective and safe tool in cancer immunotherapy." (PMID 31195686, 2019). "Mel-14 and 9.2.27 mAbs target different regions of the extracellular domain on CSPG4 and the anti-tumor efficacy of one mAb over the other is unknown." (PMID 30625226, 2019). "The expression of CSPG4 on healthy tissues is, however, clearly weaker than on tumor cells." (PMID 31426437, 2019).
tumor (continued). "To circumvent concerns about potential on-target/off-tumor toxicities, we have previously demonstrated that transient transfection of T cells with CSPG4-CARs using mRNA electroporation might be an effective and safe tool in cancer immunotherapy." (PMID 31426437, 2019). "In sum, CSPG4-CAR-T cells could exert a dual hit on GBM by concomitantly targeting GSCs and tumor-associated vasculature." (PMID 31779130, 2019). "Finally, CSPG4 is an important factor in orchestrating tumor neovascularization, which is crucial for the supply with oxygen and nutrients, but also for dispatching metastases to other sites, such as the liver." (PMID 31779130, 2019). "Since CSPG4 activated signaling pathways are known to be involved in tumor cell growth, adhesion, migration, and chemoresistance we analyzed the in vitro effect of 9.2.27-PE38KDEL/ABT-737 mono or combination therapy on FAK, PKCα, and AKT pathways in D-10-0021 MG, DM440, and SUM159-R113 cells." (PMID 30625226, 2019). "In this study, among the 26 RCC cases, PD-L1-positive rate in tumor cells was significantly higher in specimens with 4 somatically mutated genes, including CSPG4, DNAH11, INADL and TMPRSS13, than in samples without those (P < 0.05)." (PMID 30349421, 2018). "Therefore, we utilized Col1a1FRT-STOP-FRT-Cre-ER-T2/+ mice for sequential mutagenesis restricted to the sarcoma cells to investigate the role of tumor-specific Ng2/Cspg4 in tumor maintenance." (PMID 29196603, 2018). "CSPG4 displayed a less striking difference between tumour groups." (PMID 29058119, 2018). "Among the 26 RCC cases, the PD-L1-positive rate in tumor cells was higher in samples with the 4 somatically mutated genes, including CSPG4, DNAH11, INADL and TMPRSS13, than in samples without those (P > 0.05)." (PMID 30349421, 2018). "Thus, the human tumors behave similarly to the mouse tumors in which Ng2/Cspg4 is depleted in an established tumor." (PMID 29196603, 2018). "Notably, only a specific type of pericyte, expressing both NG2/CSPG4 and Nestin, would be recruited during tumor angiogenesis." (PMID 30213051, 2018). "Antigens that display high constitutive expression that is tumor-restricted (e.g., chondroitin sulfate proteoglycan 4) may permit the application of CAR T cell therapy to higher proportions of patients and reduce the likelihood of tumor escape." (PMID 30559740, 2018). "When Ng2/Cspg4 is depleted at the time of tumor initiation, many of these genes are down-regulated." (PMID 29196603, 2018). "Importantly, in order to develop more successful therapeutics, a better understanding of the functions of CSPG4 in cancer and its interaction with the immune system and the tumor immune stroma are urgently needed." (PMID 29375561, 2017). "Herein, binding of bsAb MCSPxDR5 to tumor cells appeared to be dominated by binding to CSPG4." (PMID 28657611, 2017). "Specifically, the over-expression of CSPG4 could sustain a high proliferative phenotype of tumor cells." (PMID 28668095, 2017). "Advanced T classification (p = 0.007), T3-T4 grouping (p = 0.001), positive NG2/CSPG4 transcript expression (p = 0.029), or GPC1 positivity in stromal cells (p = 0.007) were all conditions strongly associated with a high loco-regional tumour relapse rate." (PMID 25935541, 2015). "Appearance of NG2/CSPG4, a PG with a precedent prognostic impact in numerous solid tumours, was found to tightly correlate with loco-regional tumour recurrence and, hence, was disclosed to be the first ever to be described molecular relapse predictor in oral cavity HNSCC." (PMID 25935541, 2015). "This was not reflected in the oxygenation levels underlining the role of CSPG4 irrespective of oxygenation in tumor microenvironment and showing its potential as a therapeutic target." (PMID 25997619, 2015). "Unsorted PBMC killed 81% CSPG4 positive tumor cells, here 19% viable cells were left." (PMID 26469402, 2015). "Surficial retention on tumor cells renders CSPG4 an attractive therapeutic target." (PMID 24932730, 2014).